LOX (lysyl oxidase)
Diseases named in the same sentence as LOX in open-access papers (continued):
Sharing a sentence is not in itself a finding about the gene and the disease.
tumor (continued). "Mediators secreted from the primary tumor can activate lung fibroblasts to deposit more fibronectin, periostin and lysyl oxidase (LOX), thus enhancing the attachment of bone marrow derived cells (BMDCs) and of DTCs." (PMID 40370456, 2025). "The results were consistent with our expectations: CCL5, LOX, and C3 were significantly upregulated in tumor tissues, whereas PLG exhibited markedly higher expression in normal tissues." (PMID 40396123, 2025). "The results demonstrated a significant decrease in the expression of Ki67 protein in tumor tissues from sh-LOX, sh-LOXL1, sh-LOXL2, sh-LOXL3, and sh-LOXL4 mice, compared to the sh-NC group." (PMID 40270974, 2025). "The results indicated a significant increase in the expression of INF-γ and TNF-α in the tumor tissues of mice from the sh-LOX, sh-LOXL1, sh-LOXL2, sh-LOXL3, and sh-LOXL4 groups compared to the sh-NC group." (PMID 40270974, 2025). "Studies have linked higher fish consumption to reduced cancer risk and slower tumor growth, primarily attributed to fatty acids like EPA and DHA and the inhibition of LOX metabolites." (PMID 41304959, 2025). "Preliminary observations indicate a decrease in the tumor volume and weight of mice in the sh-LOX, sh-LOXL1, sh-LOXL2, sh-LOXL3, and sh-LOXL4 groups compared to the sh-NC group." (PMID 40270974, 2025). "Intriguingly, this analysis also revealed enrichment in high‐Cu zones for multiple known tumor metastatic markers, including LOX (copper‐dependent enzymes as well as a tumor migration marker), vimentin, and collagen I." (PMID 40270472, 2025). "The differential EMT analysis highlighted the LOX gene’s role in promoting tumor invasiveness and metastasis." (PMID 40165301, 2025). "We have shown that ECM remodeling, driven by factors such as MMPs and LOX, not only facilitates tumor invasion and chemoresistance but also creates a dynamic microenvironment that actively shapes cancer progression." (PMID 40149289, 2025). "Integrins also modulate the tumor stroma, with LOX‐mediated matrix stiffening and bulky glycocalyx structures promoting integrin signaling and tumor survival." (PMID 40304052, 2025). "In our study, the radiomic model of the whole‐tumor and peri‐tumor region also has good predicting effect in the expression of LOX." (PMID 40792413, 2025). "LOX also participates in the differentiation, malignant transformation, and invasiveness of tumor cells as a classic hypoxia‐induced gene." (PMID 40792413, 2025). "Lactate oxidase (LOx) catalyses the conversion of lactate to pyruvate while generating reactive oxygen species (ROS), thus exerting a synergistic anti‐tumour effect." (PMID 40984037, 2025). "Reports have also identified that reducing collagen cross-linking through lysyl oxidase inhibition enabled more efficient T cell infiltration into the tumor, leading to improved anti-PD-1 treatment." (PMID 41199904, 2025). "According to our research, regions of tumours with high LOX and LOXL2 levels also had higher expression of CD68 and CD206, which were known to be markers of macrophages and M2 macrophages, respectively." (PMID 40179101, 2025). "This tumor-autonomous molecular driver promotes collagen fiber alignment via lysyl oxidase catalysis, resulting in a biomechanically reinforced microenvironment that enhances cooperative tumor cell invasion." (PMID 41250755, 2025). "By producing LOX, CAFs crosslink collagen, restructure the stroma, and increase matrix stiffness, creating a favorable niche for tumor cell growth." (PMID 40721833, 2025). "The model of the whole‐tumor and peri‐tumor region also has a good predicting effect in LOX expression, with the area under the ROC curve being 0.800 in the training set, while the average AUC value of the 5‐fold cross‐validation was 0.796." (PMID 40792413, 2025). "They secrete extracellular matrix (ECM)-remodeling enzymes, such as matrix metalloproteinases (MMPs) and lysyl oxidase (LOX), which create pathways for tumor invasion." (PMID 41311372, 2025).
tumor (continued). "By secreting collagen, fibronectin, and lysyl oxidase, myCAFs contribute to the desmoplastic reaction, which increases tissue stiffness and forms physical barriers that support tumor invasion and hinder the delivery of drugs." (PMID 40940809, 2025). "CAFs and TAMs were found to be enriched in tumour regions characterised by enhanced expression levels of LOX and LOXL2 compared to regions with lower expression levels of these proteins." (PMID 40179101, 2025). "In a liver orthotopic xenograft model, reducing tumor ECM stiffness by inhibiting LOX enzyme activity significantly enhanced the efficacy of sorafenib and suppressed tumor progression." (PMID 40685383, 2025). "The expression level of LOX in tumor tissues was significantly higher than that in normal tissues, with a median difference of 0.45469 (95% confidence interval [CI], 0.31836–0.61311, p < 0.001)." (PMID 40792413, 2025). "Considering that intracellular LOX activity contributes to tumor progression, we developed a LOX-blocking antibody that specifically targets extracellular LOX activity." (PMID 40685383, 2025). "LOX-mediated collagen crosslinking is a key mediator of increased tumor stromal stiffness and a driver of metastatic tumor growth." (PMID 40574854, 2025). "Inhibition of lysyl oxidase has been shown to delay tumor progression, decrease tumor burden, and preferentially lead to low-grade tumor formation using the MMTV-Neu murine models for breast cancer progression." (PMID 39716322, 2024). "LOX is now being recognized as a promising therapeutic target because of its dual involvement in the tumor stroma and premetastatic niche formation." (PMID 39697341, 2024). "Studies in tumour cells have shown that HIF-1α can mediate LOX expression by binding to HREs in the LOX promoter so that intensive ECM remodelling can occur to meet the demand for tumour cell invasion and metastasis." (PMID 38333108, 2024). "In breast cancer, the LOX-mediated collagen I crosslink increases tumor cell proliferation and enhances metastatic colonization and growth." (PMID 39682261, 2024). "The copper-dependent lysyl oxidase (LOX) family contributes to tumor metastasis, and its activity is dependent on the expression of ATP7A." (PMID 38200525, 2024). "Current studies have discovered that various LOX pathway metabolites, such as HETEs, play a role in inhibiting tumor cell apoptosis, stimulating angiogenesis, enhancing cell proliferation, and promoting metastasis." (PMID 38764576, 2024). "A variety of novel LOX2 inhibitors or LOX inhibitors are being evaluated in early clinical trials, and their future combination with chemotherapy is expected to become a new method for anti-tumor treatment." (PMID 39682291, 2024). "Through mathematical modeling, it has been shown that migration of cancer cells is enhanced in the presence of LOX-mediated fiber cross-links, highlighting the importance of LOX during tumor invasion." (PMID 38495620, 2024). "Dual inhibition of LOX and CLOCK-OLFML3 axis extends the survival of PTEN-deficient GBM-bearing mice and leads to disease eradication in majority of tumor-bearing mice when combined with anti-PD1 therapy." (PMID 39352749, 2024). "Upregulation of LOX also improves the resistance to anticancer therapeutic agents by preventing their penetration to the inner area of the tumor." (PMID 39329988, 2024). "CAFs, the primary provider of ECM, alter the tumor microenvironment via the expression of LOX, which induces collagen crosslinking during tumor advancement, which is tightly linked to ECM denseness and constitution." (PMID 38201302, 2024). "LOX has been found to not only modulate the behaviour of local cells at the primary site, but also at distant secondary sites prior to tumour cell arrival." (PMID 38468823, 2024). "In the hypoxic environment of tumour cells, increased levels of LOX and LOXL2 result in irregular collagen alignment, leading to matrix restructuring." (PMID 39247609, 2024).
tumor (continued). "Recent research has revealed that LOX, produced by hypoxic tumour cells, plays a significant role in the formation of the premetastatic niche." (PMID 39247609, 2024). "Immunofluorescence (IF) staining demonstrated that treatment with BAPN or LOX-neutralizing antibodies in tumor-bearing C57BL/6J mice increased intratumoral CD8+ T cells and activated CD8+ (CD8+CD69+) T cells." (PMID 39352749, 2024). "In the TME, YAP/TAZ, Rho/ROCK, FAK, and LOX are the main mechanotransducers that are mostly overexpressed in tumor tissues and regulate macrophage polarization and function stimulated by matrix stiffness and mechanical force." (PMID 38246995, 2024). "The majority of these tumor specimens were derived from iCCA, and LOX isoform expression maintained its prognostic value in this cohort." (PMID 39101793, 2024). "The hypoxic TME increases tumor cell expression of LOX and promotes collagen covalent crosslinking, which increases matrix stiffness." (PMID 38659022, 2024). "A significant increase in the expression of LOX in early LUAD coincides with the infiltration of the primary tumor by immune cells." (PMID 39329988, 2024). "Hypoxia in the primary tumor upregulates lysyl oxidase, which cross-links collagen, increasing ECM stiffness and allowing tumor cell migration and immune evasion." (PMID 39594665, 2024). "The level of LOX also indicates a correlation with the TNM (tumor–node–metastasis, a widely used classification to describe the extent of cancer) stage of the disease." (PMID 39329988, 2024). "Pan-LOX inhibition reversed mechanical compression of tumor vasculature, resulting in improved chemotherapeutic penetrance and cytotoxic efficacy." (PMID 39101793, 2024). "While IGFBP2 and CP displayed more expression in the cellular tumor zone toward the tumor center, LOX was expressed in the vascular regions at the periphery." (PMID 38339384, 2024). "We found that LOX+ Fibroblasts were significantly enriched in tumor tissue compared to normal mucosa by evaluating the composition of each fibroblast subtype." (PMID 39251966, 2024). "Together, these findings suggest that modulation of tumor stroma through pan-LOX inhibition primes the TME for improved responses to systemic therapy." (PMID 39101793, 2024). "For instance, the knockdown of LOX in human LUAD cells represses their invasion and migration, suggesting that specific inhibitors of LOX would be capable of slowing down tumor growth and metastasis in LUAD patients." (PMID 39329988, 2024). "LOX promotes the growth of metastatic tumours through various mechanisms, including altering the extracellular matrix, attracting CD11b+ bone marrow cells, and facilitating their infiltration into the premetastatic microenvironment." (PMID 39247609, 2024). "Further analysis revealed that differentiation status, tumor stage, LOX expression, and ACSL5 expression were independent factors predicting prognosis." (PMID 39108264, 2024). "Consistent with our previous result, the abundance of LOX+ Fibroblast in tumor tissue was substantially higher than in nearby normal one." (PMID 39251966, 2024). "Lysyl oxidase (LOX), the enzymes responsible for crosslinking collagen, has been identified as upregulated in tumor-primed RDEB mice due to increased TGFβ signaling, and leading to increased ECM stiffness." (PMID 38462666, 2024). "In the tumor microenvironment, LOX expression is typically significantly increased, leading to abnormal matrix stiffening and fibrosis." (PMID 38690275, 2024). "Experimental evidence that pyruvate dehydrogenase kinase 1 (PDK1) and lysyl oxidase (LOX) genes associated with hypoxia is associated with tumor metastasis and survival, while decorin (DCN) can inhibit tumor." (PMID 38800967, 2024). "Pan-LOX inhibition with PXS-5505 reduces chemotherapy-induced mechanical compression of tumor vasculature to improve chemotherapeutic delivery and efficacy." (PMID 39101793, 2024).
tumor (continued). "These fibres are crosslinked by specific enzymes including lysyl oxidase (LOX) which regulates the stiffness of tumours and induces fibrosis." (PMID 38352889, 2024). "Chemical inhibition of LOX activity using β-Aminopropionitrile (BAPN) has been shown to increase tumor latency and decrease tumor incidence in the mouse mammary tumor virus (MMTV)-Neu model." (PMID 38238542, 2024). "The association between LOX and cytokines secreted by CD8+ T cells, such as TNF-α or IL-4, reinforces the fact that immune cells have a strong impact on ECM remodeling and tumor cell dormancy exit." (PMID 39682261, 2024). "ECM-modifying enzymes such as lysyl oxidase (LOX) and transglutaminase expressed by tumor cells further promote covalent cross-linking and linear arrangement of fibers." (PMID 39085965, 2024). "LOX-inhibitor reduces tumor stiffness, increases tumor-infiltrating T cells, and improves anti-PD-1 response." (PMID 39697341, 2024). "LOX also contributes to the structural rearrangements of the tumor microenvironment (TME) by surrounding the tumor with a dense layer of ECM proteins." (PMID 39329988, 2024). "The H-scores of MAOA (T; p = 0.005) and MAOB (T; p = 0.006) in tumor cells (T) were high in ACN, whereas LOX (T, S; p < 0.001) in tumor and stromal cells (S) and AOC3 (T; p < 0.001) were higher in PCC." (PMID 37509535, 2023). "Lysyl oxidase is a secreted copper-dependent monoamine oxidase that catalyzes the covalent crosslinking of collagen and elastin via oxidation in the tumor microenvironment." (PMID 37891828, 2023). "Hypoxia-induced increased expression level of several ECM remodeling enzymes such as LOX and collagen prolyl 4-hydroxylase (C-P4H) has been reported to mediate modification on collagens and promote tumor progression." (PMID 36906534, 2023). "Among them, LOX played a critical role in tumor immune microenvironment and influenced tumor cell proliferation, was also upregulated in early ESCC (fold change = 6.39, P value = 0.01)." (PMID 37393256, 2023). "Nanoparticles can carry two or more fluorescent probes at the same time, which can specifically identify tumor cells and the overexpression of the protease family (LOX, MMPs, etc.)around the tumor, so as to achieve multiple recognition." (PMID 36839868, 2023). "Our in vitro studies further support that wildtype LOX-PP (Arg LOX-PP) inhibits LOX expression in an oral-tumor cell line, while mutant LOX-PP (Gln LOX-PP) has a reduced inhibitory effect." (PMID 37298359, 2023). "The presence and activity of LOX as well as the expression of fibrillar collagen were considerably elevated in the lungs of surgically treated mice, which led to tumor cell seeding and lung metastasis." (PMID 37468874, 2023). "Immunofluorescent staining of 4 NQO tumor lesions indicated that a significant increase in PD-L1 production was observed in the lesions of knockin Gln LOX-PP mice compared to wildtype Arg LOX-PP mice, and this production was not by CD4+ T cells." (PMID 37298359, 2023). "LOX is an ECM remodeling enzyme that is abundantly expressed in the tumor microenvironment and plays an important role in tumorigenesis and in lowering the tumor response to anticancer drugs and also confers chemoresistance." (PMID 35138531, 2023). "According to a study applying CRISPR/Cas9 to silence ATP7A,the activity of LOX was inhibited in breast cancer and lung cancer cell lines,suppressing these tumor cell growth and migration." (PMID 36925927, 2023). "Both angiogenesis and metastasis were suppressed with LOX inhibitors during carcinogenesis examined in vivo, and the decrease in LOX expression inhibited cell migration and neovascular formation in tumor endothelial cells." (PMID 38139406, 2023). "Hypoxia stimulates LOX expression and increase collagen crosslinking and tumor invasion in ovarian cancer." (PMID 36906534, 2023).
tumor (continued). "In a further way, copper can also promote the synthesis of FGF-1 through ATOX1 and superoxide dismutase 1 (SOD1) to affect vascular endothelial function, while increasing the invasive and metastatic capacity of tumor cells by activating lysyl oxidase (LOX)." (PMID 37476384, 2023). "With regard to potential applications of first-generation lysyl oxidase inhibitors in the therapy of tumour diseases, reductively activatable βAPN prodrugs deserve special mention." (PMID 37565736, 2023). "LOX is induced by hypoxic conditions in the tumor and its pro-tumorigenic role has been well described." (PMID 37190331, 2023). "In vivo, injection of MCF10AT cells into mammary fat pads conditioned with LOX-overexpressing fibroblasts led to increased tumor growth and invasion." (PMID 37296891, 2023). "The primary tumor-derived or local production of LOX enzymes (LOX and LOXL2) along with the increase in FNs and collagen creates a profibrotic lung microenvironment that is conducive to PMN formation and further supports inflammation and immunosuppression." (PMID 37350937, 2023). "This hypoxia–LOX–stiffness relationship was further corroborated by the strong positive correlation between cell death and tumor ECM stiffness, which was only established after NTD treatment." (PMID 37190331, 2023). "In the context of tumor scenarios, an elevation in LOX expression results in an excessive cross-linking of collagen." (PMID 38332915, 2023). "The lipid metabolism involved in LOX in TAMs not only promotes the formation of an immunosuppressive microenvironment but also promotes the proliferation of tumor cells." (PMID 37004014, 2023). "Inhibition of LOX activity, one of the well-known molecules for matrix stiffness, reduced tumor progression and metastasis in mice." (PMID 37468874, 2023). "Nanoparticles can be applied to recognize not only tumor cells, but also matrix metalloproteinases (MMPs) or lysyloxidase (LOX) in the tumor microenvironment (TME), thus realizing dual-recognition." (PMID 36839868, 2023). "The lysyl oxidase (LOX) enzyme is responsible for the crosslinking of collagen I. The inhibition of LOX resulted in decreased stiffness and increased tumor latency." (PMID 36980785, 2023). "In hypoxic TNBC cells, HIF1α also drives lysyl oxidase (LOX) expression to regulate the tumor microenvironment via downstream integrin/FAK signaling and, as a result, confers resistance to chemotherapeutic agents." (PMID 37583933, 2023). "LOX is a tumor-secreted protein increased in hypoxia and is found to be critically involved in premetastatic niche formation." (PMID 37786649, 2023). "In a mouse model of breast cancer, knockdown of ATP7A reduced LOX activity, decreased the recruitment of bone marrow cells to the lung, and inhibited tumor growth and metastasis." (PMID 37600770, 2023). "The propeptide of LOX is released as an 18 kDa protein (LOX-PP) in the extracellular environment by procollagen C-proteinases and has tumor-inhibitory properties." (PMID 37298359, 2023). "Hypoxia in primary tumor induces the expression of lysyl oxidase (LOX), which crosslinks collagen in the ECM in the lungs." (PMID 35203510, 2022). "A low expression of LOX was observed in EwS and the ectopic expression of LOX impaired xenograft tumor formation in vivo." (PMID 35740349, 2022). "VEGF is a known regulator of bone resorption, while lysyl oxidase (LOX) release is driven by signaling of hypoxia inducible factors (HIF) to promote invading tumour cell colonisation and osteolysis at skeletal sites." (PMID 35754558, 2022). "This study suggested that LOX inhibition can improve ECM to reduce tumor stiffness, and subsequently facilitate T cell migration and improve anti-PD-1 efficacy." (PMID 36293126, 2022). "Recent studies have found that LOX participates in the construction of the tumor immunosuppressive microenvironment." (PMID 36293126, 2022).